SLCO1B1 (solute carrier organic anion transporter family member 1B1)
Diseases named in the same sentence as SLCO1B1 in open-access papers (continued):
Sharing a sentence is not in itself a finding about the gene and the disease.
liver fibrosis (4 papers, 2018 to 2026). "In this study, we found that SLB-M treatment ameliorated liver fibrosis by reducing collagen deposition and restoring tissue integrity by promoting the Fxr to appropriately decrease conjugated BAs by promoting Slco1a1, Slco1b1, and Sult2a8 expression." (PMID 39452937, 2024). "We evaluated whether HLA-DRB1, PNPLA3, SLCO1B1, and MTHFR variants are associated with NAFLD, liver fibrosis, or MTX toxicity/pharmacokinetics in RA, after accounting for clinical covariates." (PMID 41753255, 2026).
Peptic ulcer (4 papers, 2013 to 2022). The term peptic ulcer refers to acid peptic injury of the digestive tract, resulting in mucosal break reaching the submucosa. "Different studies have previously shown the association of the SLCO1B1 521TT genotype and the SLCO1B1*1b haplotype with the risk of aspirin induced peptic ulcer." (PMID 27304055, 2016). "Our recent Japanese study suggested that the SLCO1B1 521TT genotype and the SLCO1B1 *1b haplotype were significantly associated with the risk of peptic ulcer and ulcer bleeding in patients taking low dose enteric-coated aspirin." (PMID 24367646, 2013). "They found that the frequencies of the SLCO1B1*1b haplotype and CHST2 2082 T allele were higher in peptic ulcer patients." (PMID 27304055, 2016).
prostate carcinoma (4 papers, 2011 to 2023). A carcinoma that arises from epithelial cells of the prostate gland. "Moreover, SLCO1B1 overexpression in prostate tumors may also explain the sensitivity of prostate cancer to ketoconazole." (PMID 21625523, 2011). "Transcripts of SLCO1A2, SLCO1B1 and SLCO1B2 are increased 4-fold, 2.5-fold, and 1.74-fold respectively in LNCaP and 22Rv1 prostate cancer cells grown under conditions of androgen depletion to mimic ADT." (PMID 35582223, 2020). "SLCO1B1- and SLCO2B1-expressing prostate cancer xenografts showed a 3.9-fold and 1.9-fold increase in tumor accumulation of DHEA-SO4, respectively." (PMID 35582223, 2020). "Moreover, mRNA expression levels of SLCO1B1, SLCO1B3, SLCO2B1 and SLCO4C1 were found to be higher in castration-resistant prostate cancer metastases as compared to in untreated prostate cancer." (PMID 36839686, 2023).
anemia (3 papers, 2024 to 2025). A reduction in the number of red blood cells, the amount of hemoglobin, and/or the volume of packed red blood cells. "Significant associations were found between SLCO1B1 (rs2306283) and gastrointestinal disturbances and anemia." (PMID 40732356, 2025). "A similar result was reported in a previous study, indicating that the SLCO1B1 rs2306283 GG genotype is associated with an increased risk of MTX-induced anemia." (PMID 40732356, 2025).
Gilbert syndrome (3 papers, 2022 to 2026). An autosomal recessive inherited disorder characterized by unconjugated hyperbilirubinemia, resulting in harmless intermittent jaundice. "Bilirubin is downstream of a large number of metabolic processes, and as such, most genetic variants that affect bilirubin (outside the Gilbert syndrome risk locus) are involved in other health processes (eg, cholesterol metabolism for SLCO1B1)." (PMID 37456363, 2023).
Hepatitis (3 papers, 2022 to 2024). Inflammation of the liver. "Duplications on CD274 (p = 0.043) and CNVs on SLCO1B1 (p = 0.010) were significantly linked to hepatitis." (PMID 35053465, 2022). "CNVs on IL1RN and deletions on PRDM1 were significantly linked to IRAE, whereas duplications on CD274 and CNVs on SLCO1B1 were significantly linked to hepatitis." (PMID 35053465, 2022). "Furthermore, the following genetic alterations were identified being associated with IRAE: SMAD3 (pancreatitis); CD274, SLCO1B1 (hepatitis); PRDM1, CD274 (encephalitis); PRDM1, CD274, TSHR, FAN1 (myositis)." (PMID 35053465, 2022). "Regarding CNVs, significant markers included PRDM1 deletions and IL1RN (IRAE), CD274 duplications and SLCO1B1 (hepatitis), PRDM1 and CD274 (encephalitis), and PRDM1, CD274, TSHR, and FAN1 (myositis)." (PMID 35053465, 2022).
Hypercholesterolemia (3 papers, 2024). An increased concentration of cholesterol in the blood. "Thus, the primary goal of this investigation was to establish the role of the SLCO1B1 c.521T>C variant on plasma AVA concentrations in pediatric hypercholesterolemia." (PMID 38254988, 2024). "This clinical study examined the influence of SLCO1B1 c.521T>C (rs4149056) on plasma atorvastatin concentrations in pediatric hypercholesterolemia." (PMID 38254988, 2024).
Hypertension (3 papers, 2015 to 2025). The presence of chronic increased pressure in the systemic arterial system. "A cohort of 450 patients with essential hypertension taking 10 mg enalapril maleate were genotyped for the functional SLCO1B1 variants, 388A > G (Asn130Asp, rs2306283) and 521T > C (Val174Ala, rs4149056)." (PMID 26607661, 2015). "In summary, our findings propose that common genetic variants in SLCO1B1 may serve as a novel pharmacogenetic biomarker for enalapril-induced cough in Chinese essential hypertensive patients because the SLCO1B1 521T > C polymorphism was associated with an increased risk of enalapril-induced cough." (PMID 26607661, 2015).
hypothyroidism (3 papers, 2019 to 2025). Abnormally low levels of thyroid hormone. "Additional risk factors include hepatic or renal impairment, co-medication with CYP3A4 inhibitors, co-medication with SLCO1B1 inhibitors, female gender, old age (≥ 65) or hypothyroidism." (PMID 31196067, 2019).
ischemic stroke (3 papers, 2024). A stroke disorder caused by obstruction of blood flow to the brain, due to thrombotic (local blood clot formation) or embolic (due to a blood clot or other material traveling from another site) event. "In this study, we investigated the relationship between gene polymorphisms, particularly SLCO1B1 and homocysteine (Hcy) concentrations in ischemic stroke patients, with a focus on identifying potential risk factors for elevated Hcy levels." (PMID 39944478, 2024). "The colocalization analysis did not reveal a shared causal variant between indirect bilirubin and the risk of ischemic stroke, based on the examination of 3 genes: UGT1A1, SLCO1B1, and SLCO1B3." (PMID 39210787, 2024). "In order to prove the study conclusion, we then selected 30 ischemic stroke patients and 244 non-stroke patients to prove the relationship between SLCO1B1 gene polymorphism and Hcy, which further confirmed our study conclusion." (PMID 39944478, 2024).
mucositis (3 papers, 2012 to 2024). Mucositis is inflammation and damage of the mucous membranes lining the mouth and other parts of the gastrointestinal (GI) tract. "In our study, patients with the SLCO1B1 rs4149056 C allele had a lower risk of developing mucositis." (PMID 28525903, 2017). "With regard to SLCO1B1 rs4149056, patients with the C allele had a lower risk of developing mucositis." (PMID 28525903, 2017). "One previous study found that SLCO1B1 rs4149056 was associated with the risk of mucositis; however, this association was not replicated in two other studies." (PMID 28525903, 2017).
pancreatic cancer (3 papers, 2011 to 2023). "SLCO1B1 expression in pancreatic cancer has been investigated as a potential target for selective toxicity to microcystin cyclopeptides." (PMID 32388639, 2020). "SLCO1B1 overexpression has been demonstrated in colonic, ovarian, prostate and pancreatic cancers." (PMID 32388639, 2020).
Stroke (3 papers, 2023 to 2024). Sudden impairment of blood flow to a part of the brain due to occlusion or rupture of an artery to the brain. "Other biomarkers investigated related to SLCO1B1 from the GWAS (Genome-Wide Association Study) Catalog included vitamin D (risk factor for muscle weakness) and bilirubin (possible risk factor for increased stroke)." (PMID 38674010, 2024). "The lowest stroke rates were for SLCO1B1*5 carriers (2.38%), and the highest rates were for SLCO1B1*20 carriers (2.8%)." (PMID 38674010, 2024). "Multiple variants in the SLCO1B1, PRIM1, APOB, TYK2, TSEN15, CYP4F2, and MST1 genes were previously suggested as risk factors for stroke with p-values < 1.0 × 10−5 in a GWAS on German pediatrics." (PMID 37895268, 2023).
acute myeloid leukemia (2 papers, 2021). Acute myeloid leukemia (AML) is a group of neoplasms arising from precursor cells committed to the myeloid cell-line differentiation. "SLCO1B1 rs2291075 was a functional genetic polymorphism associated with treatment outcome in acute myeloid leukemia and urine arsenic metabolites." (PMID 33386894, 2021). "The transporter SLCO1B1 has an important role in the system pharmacokinetics of multiple drugs used in the treatment of acute myeloid leukemia (AML)." (PMID 33386894, 2021).
Alpha-thalassemia (2 papers, 2016 to 2018). Alpha-thalassemia is an inherited hemoglobinopathy characterized by impaired synthesis of alpha-globin chains leading to a variable clinical picture depending on the number of affected alleles. "The other gene variants – including G6PD, blood type, alpha thalassemia, HO-1, and SLCO1B1 – did not carry significant difference." (PMID 30287871, 2018). "The other gene variants – including blood type, alpha thalassemia, and SLCO1B1 – carried no significant risk." (PMID 27557546, 2016).
Cough (2 papers, 2015 to 2024). A sudden, audible expulsion of air from the lungs through a partially closed glottis, preceded by inhalation. "As a significant effect of sex on the risk of enalapril-induced cough was observed, we further analyzed the association of SLCO1B1 genotypes separately by sex." (PMID 26607661, 2015). "Association of SLCO1B1 genetic polymorphisms with the risk of ACE-Is-induced cough." (PMID 39295941, 2024). "SLCO1B1 521C allele conferred a 2-fold relative risk of enalapril-induced cough (95% confidence interval [CI] = 1.34–3.04, P = 6.2 × 10−4), and haplotype analysis suggested the relative risk of cough was 6.94-fold (95% CI = 1.30–37.07, P = 0.020) in SLCO1B1*15/*15 carriers." (PMID 26607661, 2015). "We found that the association between SLCO1B1 388A > G genotypes and enalapril-induced cough remained not significant both in men and women." (PMID 26607661, 2015). "Therefore, the different frequencies of SLCO1B1 haplotypes may explain the different incidence of enalapril-induced cough in different racial populations." (PMID 26607661, 2015).
dyslipidemia (2 papers, 2021 to 2025). "Xinjiang is a multi-ethnic area; however, little is known about the prevalence of dyslipidemia and gene polymorphisms of ABCB1 and SLCO1B1 in minority groups with CHD." (PMID 34563206, 2021).
gallstones (2 papers, 2013 to 2022). Solid crystalline precipitates in the biliary tract, usually formed in the gallbladder, resulting in the condition of cholelithiasis. "Functional variants in the SLCO1B1 gene, encoding the OATP1B1 transporter, were associated with liver uptake of ERAs and gallstone formation." (PMID 36258237, 2022).
heart failure (2 papers, 2017 to 2023). Inability of the heart to pump blood at an adequate rate to meet tissue metabolic requirements. "A SNP in SLCO1B1, monomorphic in Caucasians, has also been implicated in both levels of hexadecanedioate and risk heart failure in African Americans." (PMID 28403188, 2017). "Other study did not associate slow OATP1B1 transporters, or SLCO1B1 variant carriers, with reduced risk for kidney and heart failure in Diabetic Kidney Diseases patients." (PMID 37239884, 2023).
liver diseases (2 papers, 2025). "SLCO1B1, SLCO1B3, and SLCO2B1 are highly expressed in the liver and play key roles in many liver diseases." (PMID 40734706, 2025). "SLCO1B1, SLCO1B3, and SLCO2B1 are highly expressed in the liver and play key roles in various liver diseases." (PMID 40734706, 2025).
muscular disease (2 papers, 2016 to 2019). Myopathy is a peripheral nervous system disease consisting of any abnormal condition or disease of the muscular tissues; commonly designates a disorder involving skeletal muscle. "Furthermore, CC compared to CT genotype confirmed these results, with SLCO1B1*5 CC individuals showing a higher risk of muscular disease." (PMID 30939847, 2019). "Furthermore, regarding patients with hyperlipidemia treated with simvastatin only, carrying the SLCO1B1*5 (CC/CT vs. TT) allele was associated with higher risk of muscular diseases." (PMID 30939847, 2019). "Selecting the link for SLCO1B1 under the CTD References area, ToxEvaluator opens the SLCO1B1–Muscular Diseases references page at CTD, providing the user with publications supporting the relationship between SLCO1B1 and muscular diseases." (PMID 27161010, 2016).
neuropathy (2 papers, 2023 to 2026). A disorder affecting the nervous system that manifests with pain, tingling, numbness, and/or muscle weakness. "Using targeted sequencing, they searched for variants in SLCO1B1 among other genes in a cohort of 228 patients: 131 with grade 2–3 neuropathy and 97 with grade 0–1 neuropathy." (PMID 37251592, 2023). "Emerging evidence also links additional genetic variants to toxicities associated with other key agents used in ALL treatment regimens, including variants in SLCO1B1 associated with methotrexate-related gastrointestinal toxicity and variants in CEP72 associated with vincristine-induced neuropathy." (PMID 42239520, 2026).
osteosarcoma (2 papers, 2023 to 2025). A usually aggressive malignant bone-forming mesenchymal neoplasm, predominantly affecting adolescents and young adults. "Katja Goričar conducted a prognostic analysis on osteosarcoma patients undergoing HD-MTX therapy and discovered that SLCO1B1 (1865+4846T>C) C allele was associated with a higher event-free survival." (PMID 37731501, 2023). "Notably, these findings in patients with ALL may not universally apply to other MTX-sensitive diseases, demonstrated by the lack of a significant association between SLCO1B1 SNPs and MTX clearance in patients with osteosarcoma." (PMID 40732356, 2025).
pulmonary TB (2 papers, 2017 to 2025). "Furthermore, research involving pulmonary TB patients from Africa and the USA revealed that a variant g.—11187G>A in solute carrier organic anion transporter family member 1B1 (SLCO1B1) rs4149015 was associated with an increase in both the AUC0–24 and Cmax of moxifloxacin." (PMID 40001447, 2025). "In conclusion, the high interindividual variability in plasma exposure to RIF among Malawian adults with pulmonary TB cannot be explained by genetic heterogeneity in SLCO1B1, as suggested from other African populations." (PMID 28461315, 2017).
schizophrenia (2 papers, 2024 to 2025). A major psychotic disorder characterized by abnormalities in the perception or expression of reality. "Therefore, the SLCO1B1 polymorphisms and plasma levels of N‐desmethylclozapine as well as clozapine in patients with schizophrenia should be assayed for optimizing clozapine therapy." (PMID 40740505, 2025). "We investigated the effects of age, sex, and genetic polymorphisms in CYP isoforms (CYP1A2, CYP2B6, CYP2C19, CYP2D6, and CYP3A5) and drug transporters (ABCG2 and SLCO1B1) on the plasma concentrations of clozapine, N‐desmethylclozapine, and clozapine N‐oxide in Japanese patients with schizophrenia." (PMID 40740505, 2025). "DNA was isolated from the peripheral blood samples of 27 patients with schizophrenia receiving clozapine maintenance treatment, and the pharmacokinetics‐related genes (CYP1A2, CYP2B6, CYP2C19, CYP2D6, CYP3A5, ABCG2, and SLCO1B1) were genotyped." (PMID 40740505, 2025).
serous ovarian cancer (2 papers, 2017 to 2018). "In serous ovarian cancer, SLCO1B1, SLCO1C1, and SLCO6A1 were observed in a low number of samples only." (PMID 30131693, 2018). "In contrast, the SLCO1A2, SLCO1B1, SLCO1B3, SLCO1C1, SLCO2B1, and SLCO4A1 genes were amplified in 4.7–7.4% of a total of 316 patients with serous ovarian cancer, with concurrent amplification of SLCO1A2/1B1/1B3/1C1 and SLCO1B1/1B3/1C1, and also SLCO1B3/1C1." (PMID 28674494, 2017).
type 2 diabetes (2 papers, 2020 to 2024). "In addition, six loci were linked to insulin resistance, type 2 diabetes, or reduction in HbA1c levels in type 2 diabetes (APOB, HPR, TM6SF2, KSR2, JMJD1C, and SLCO1B1)." (PMID 38532495, 2024).
acute kidney injury (1 paper, 2023). Sudden and sustained deterioration of the kidney function characterized by decreased glomerular filtration rate, increased serum creatinine or oliguria. "For instance, functional SNPs of SLCO1B1 have been shown to decrease hepatic uptake activity, while the expression level of SLCO2B1 substantially declined in the small intestine of rats with acute kidney injury." (PMID 37759782, 2023).
Anxiety (1 paper, 2019). Intense feelings of nervousness, tension, or panic often arise in response to interpersonal stresses. "Common variants in MTR, PPARA, ABCC3, CALML5, CACNB2 and PCDHB10 genes were associated with deficits in neurocognitive tests performance, whereas a variant in SLCO1B1 and EPHA5 genes was associated with anxiety and depression." (PMID 31181069, 2019). "Functionally predicted germline common variants in MTR, PPARA, SLCO1B1, ABCC3, CALML5, CACNB2 and PCDHB10 genes were found to be significantly associated with deficits in neurocognitive tests performance, whereas a variant in EPHA5 gene was significantly associated with both anxiety and depression." (PMID 31181069, 2019).
autoimmune disease (1 paper, 2022). A disorder resulting from loss of function or tissue destruction of an organ or multiple organs, arising from humoral or cellular immune responses of the individual to their own tissue constituents. "Polymorphisms of SLCO1B1 have not yet been found to be associated with autoimmune diseases or IRAE." (PMID 35053465, 2022).
autosomal recessive retinitis pigmentosa (1 paper, 2022). Autosomal recessive retinitis pigmentosa (RP) is an autosomally recessive inherited retinal dystrophy leading to progressive loss of the photoreceptors and retinal pigment epithelium and resulting in blindness usually after several decades. "Mutations in the remaining four genes, namely, SLCO1B1, CNGA1, PRSS12, and PEX1, have associations with autosomal diseases, such as autosomal recessive retinitis pigmentosa and non-syndromic intellectual disability." (PMID 35912179, 2022).
cardiomyopathy (1 paper, 2013). A disease of the heart muscle or myocardium proper. "The two mostly highly associated SNPs for cardiomyopathy (rs4149018 and rs12582717; P-values <10−6) are located on Chromosome 12p12.2 in the SLCO1B1 gene, a solute carrier family member." (PMID 24324551, 2013).
cataract (1 paper, 2023). Partial or complete opacity of the crystalline lens of one or both eyes that decreases visual acuity and eventually results in blindness. "The aim of our study was to use a genetic proxy for increased statin exposure by presence of the SLCO1B1*5 allele in a large cohort of more than 36 thousand participants to elucidate the relationship between statins and cataracts." (PMID 37221222, 2023). "Multivariable logistic regression was used to test association between SLCO1B1*5 heterozygotes or homozygotes and cataracts, in subgroups having been regularly prescribed statins versus not." (PMID 37221222, 2023). "If the protective SNP-drug effect seen were due to less statin exposure in those with a SLCO1B1*5 allele we would expect to see an association of statin use with cataracts independent of confounding factors in the first step of the analysis." (PMID 37221222, 2023). "Association between SLCO1B1*5 and cataract risk in statin users has not been characterized, and stratification by SLCO1B1*5 genotype in statin users and non-users offers a valuable approach to clarifying the relationship between statin use and cataracts." (PMID 37221222, 2023).